CPHXL (cytoplasmic polyadenylated homeobox like)
Description:
Transcription factor that acts as activator.
Synonyms: CPHXL1
Gene: Protein-coding gene on chromosome 16 (75,714,131 to 75,726,490, reverse strand). Ensembl gene ENSG00000283755.
Subcellular location: Nucleus
Gene Ontology:
Molecular function: DNA-binding transcription factor activity, RNA polymerase II-specific; RNA polymerase II cis-regulatory region sequence-specific DNA binding; DNA binding
Biological process: regulation of transcription by RNA polymerase II
Cellular component: nucleus
Homologues: Orthologues: chimpanzee CPHXL (97% identical), macaque CPHXL (80% identical), mouse Cphx1 (15% identical), rat Cphx1 (13% identical), Drosophila melanogaster inv (9% identical), Drosophila melanogaster en (8% identical), Caenorhabditis elegans ceh-16 (6% identical). Paralogues in human: CPHXL2 (78% identical), EN1 (9% identical), EN2 (8% identical).